TNF (tumor necrosis factor)
Diseases named in the same sentence as TNF in open-access papers (continued):
Sharing a sentence is not in itself a finding about the gene and the disease.
metabolic syndrome (continued). "In patients with metabolic syndrome, the results presented by Alizaei Yousefabadi (2021) demonstrate a significant reduction in TNF-α, CRP, and IL-8 but an increase in IL-10 after a 12-week follow-up period." (PMID 40559680, 2025). "These processes are mediated through inflammatory cytokine activation, such as IL‐6, TNF‐α, TGF‐β1, and mitochondrial dysfunction, reinforcing the causal role of uric acid in dyslipidemia and cardiovascular disease." (PMID 41287972, 2025). "Inflammatory mediators such as TNF-α and IL-6 amplify oxidative stress and vascular injury, while dyslipidemia accelerates atherogenesis." (PMID 41227114, 2025). "Higher TNF-α with greater UPF intake was observed in Spanish older adults with metabolic syndrome (n = 92), U.S. colon cancer patients (n = 796), and an Irish primary-care sample (n = 1986)." (PMID 41010537, 2025). "This triggers systemic inflammation, with TNF-α inducing insulin resistance by inhibiting insulin receptor phosphorylation, thereby disrupting insulin signaling and contributing to dyslipidemia and T2D." (PMID 40944214, 2025). "These macrophages secrete cytokines such as TNF-α and IL-6, exacerbating the inflammation eventually resulting in lipotoxicity, systemic inflammation and contributing to IR and metabolic syndromes." (PMID 41373779, 2025). "Conversely, LDL levels were positively correlated with both CRP (r = 0.38, p < 0.05) and TNF-α (r = 0.41, p < 0.01), suggesting that dyslipidemia contributes to heightened inflammatory activity in KOA patients." (PMID 40078412, 2025). "Sarcopenia and CVD share common inflammatory pathways, including elevated cytokine levels, such as IL-6 and TNF-α, which contribute to vascular dysfunction and metabolic syndrome." (PMID 40430117, 2025). "Metabolic syndrome creates a systemic inflammatory environment characterized by elevated C-reactive protein, tumor necrosis factor-alpha, and interleukin-6 levels that can impair tissue repair processes." (PMID 41226877, 2025). "On the other hand, some egg studies have found that participants who were overweight or who had metabolic syndrome experienced a reduction in inflammatory markers after egg interventions (3 eggs/day for 4–12 weeks led to reductions in TNF-α, IL-6, and CRP)." (PMID 40647165, 2025). "This study identified lipid aggregation product (LAP), TNF-α, and HMGB1 as useful predictors of metabolic syndrome, with LAP showing the highest diagnostic value." (PMID 40871683, 2025). "For example, Heng et al7 found that administering 400 mg of TRF daily for 16 weeks resulted in a significant decrease in TC, LDL-C, HDL-C, IL-6, and tumor necrosis factor-alpha (TNF-α) in patients with metabolic syndrome." (PMID 38916919, 2025). "A relationship between certain cytokines (IL-6 and TNF-α) and E2 has been documented in male patients with metabolic syndrome." (PMID 40564184, 2025). "Within patients affected by metabolic syndrome, there is a heightened production of proinflammatory mediators, such as leptin, TNF-α, and IL-6, creating a mutually reinforcing cycle that exacerbates both conditions." (PMID 39767248, 2024). "The potent inflammatory cytokines TNF-a and IL-6 are involved in the development of metabolic syndrome and insulin resistance." (PMID 39767248, 2024). "Metabolic syndrome associated inflammatory markers such as, IL-1β, MCP-1, TLR-4 and TNF-α were quantified in dietary lipid supplemented healthy and diabetic groups." (PMID 38755663, 2024). "The concentrations of early metabolic syndrome biomarkers [adiponectin, leptin, TNF-α, IL-1, IL-6, IL-10, endothelin-1, apolipoprotein B, and lipoprotein (a)] were measured and a cardiopulmonary exercise test (CPET) was performed." (PMID 38254811, 2024). "In this context, BLE reduced oxidative stress and levels of TNF-α, IL-6 and IL-10 in the muscles of rats with metabolic syndrome." (PMID 38257152, 2024).
metabolic syndrome (continued). "Pue has an effect on obesrity-induced inflammation and dyslipidemia by decreasing the macrophages population and tumor necrosis factor-α (TNF-α) expression." (PMID 39141625, 2024). "Several lines of evidence suggested that patients with dyslipidemia exhibited higher TNF-α plasma concentrations, which correlated significantly with the concentrations of VLDL, triglycerides and cholesterol and correlated negatively with HDL cholesterol." (PMID 38684998, 2024). "It has been demonstrated that PD patients with dyslipidemia had significantly higher levels of IL-10, TNF-α, and MCP-1 in PDE compared to dyslipidemia-free patients." (PMID 39457689, 2024). "Group 2 had significantly raised serum TNF-α (128.0 pg/ml), as did group 4 obese subjects with metabolic syndrome (238.6 ± 62 pg/ml), compared to healthy controls (21.7 ± 11.8 pg/ml; p < 0.001)." (PMID 39149648, 2024). "Elevated levels of pro-inflammatory cytokines such as IL-6 and TNF-α are common in individuals with metabolic syndrome." (PMID 39310549, 2024). "Development of Metabolic Syndrome (MetS) is strictly linked to pro-inflammatory action of adipocytes as a consequence of secretion of many factors including leptin and adiponectin as well as proinflammatory tumor-necrosis factor-alpha and interleukins." (PMID 36837434, 2023). "We determined the correlation between kidney fibrosis score and phosphorylated AMPK, oxidative stress (MDA), inflammation (TNF-α), renal injury biomarkers (urea and creatinine), dyslipidemia (TG), and systemic hypertension (SBP)." (PMID 36985728, 2023). "In metabolic syndrome, the level of TNF-α changes in accordance with the change of the gut microbiota." (PMID 36768946, 2023). "EPE attenuated dyslipidemia, serum transaminases, tumor necrosis factor (TNF)-α, interleukin (IL)-1β and liver lipid accumulation, nuclear factor (NF)-κB p65, and lipid peroxidation, nitric oxide and enhanced antioxidants." (PMID 37397470, 2023). "K-FGF suppresses TNF-α production and prevents chronic inflammation-induced disorders, including metabolic syndrome." (PMID 36768946, 2023). "For the first time in Polish population of older adults with the metabolic syndrome, we determined the AUC value as well as the cut-off value for TNF-α." (PMID 36596839, 2023). "In human adipose tissue, BPA stimulates the release of cytokines favouring adiposity namely interleukin-6 (IL-6) and tumor necrosis factor alpha (TNF-α), whereas it inhibits the release of adiponectin that acts protective against metabolic syndrome." (PMID 36676087, 2023). "Pro-inflammatory cytokines, such as IL-1β, IL-6, and TNF-α, are produced in adipose tissues during pathogenesis of metabolic syndrome." (PMID 36826001, 2023). "Although the relationship between inflammation and dyslipidemia is not fully understood, epidemiological data showed that dyslipidemia patients exhibit a proinflammatory state that is characterized by higher cytokine levels, including TNF-α and IL-6." (PMID 38004051, 2023). "Pro-inflammatory cytokines like leptin, IL-6 and TNF-α are noted to be formed in adipose tissues during pathogenesis of metabolic syndrome, and the anti-inflammatory cytokine, adiponectin has the power to counteract their harmful sequels." (PMID 36826001, 2023). "All subjects with urolithiasis and metabolic syndrome were characterized by significantly higher inflammatory markers IL-6 and TNF-α, as confirmed in the literature." (PMID 36830821, 2023). "In this in vivo study, HD of EBN continues to lead in upregulating levels of PGC-1α, IL-10, SOD, and downregulation of TNF-α; which will reduce the complications of metabolic syndrome." (PMID 37764670, 2023). "Chronic inflammation has been extensively studied as a component of the metabolic syndrome due to the release of pro-inflammatory adipokines, such as leptin, interleukin-6 (IL-6), tumor necrosis factor-α (TNFα), and others, by adipose tissue." (PMID 37957462, 2023).
metabolic syndrome (continued). "High glucose levels and dyslipidemia directly induce the upregulation and secretion of cytokines such as tumor necrosis factor-alpha (TNF-α), interleukins (IL-6, IL-1β), and C-reactive protein (CRP)." (PMID 37175496, 2023). "Increased adiponectin production improves metabolic syndrome because TNF-α suppression and GLUT4 production result in the improvement of glucose intake from cells." (PMID 36768946, 2023). "Growing evidence suggests that the consumption of TFAs is associated with dyslipidemia and the activation of systemic inflammatory responses, such as elevated CRP, interleukin-6, and tumor necrosis factor." (PMID 37710270, 2023). "Considering the association between elevated TNFα and HTN, the deregulated metabolism in rodent models of HTN, as well as the high prevalence of metabolic syndrome in hypertensive patients, the role of colonic TNFα in HTN warrants further elucidation in vivo." (PMID 36830627, 2023). "During the progression of metabolic syndrome, however, adipocytes enlarge and change their shape to produce TNF-α." (PMID 36768946, 2023). "LPS, ROS, MDA, and Keap1 were significantly positively correlated with inflammatory cytokines (IL-1β, COX2, TNF-α, IL-6, and iNOS), metabolic syndrome (LDL-C, T-CHO, TG, and BUN), ABW, and ADG at 45 d, 60 d, and 90 d of sample collection." (PMID 38003191, 2023). "According to our findings, the AZGP1 gene-enriched pathway in the skeletal muscle is directly related to dyslipidemia, inflammatory response mediated by TNF-alpha and IL-1b, and metabolic diseases." (PMID 35804531, 2022). "Inflammatory markers that have been associated with metabolic syndrome are hs-CRP, TNF-α, fibrinogen, and IL-6." (PMID 35736651, 2022). "The study showed that the five classified types of dyslipidemia had increased circulating levels of IL-6, TNF-α, and MCP-1 compared with a normal lipid group in male adults." (PMID 36032093, 2022). "LGZG, combined with dietary restriction and regular exercise, decreased the levels of TG, TC, LDL-c, and FFA in rat of metabolic syndrome, possibly due to the inhibition of the serum and liver levels of TNF-α, leptin, and PKB." (PMID 35586687, 2022). "Patients with metabolic syndrome have elevated serum levels of proinflammatory mediators such as tumor necrosis factor-alpha interleukin-6 and C-reactive protein." (PMID 36361416, 2022). "Dyslipidemia also plays a pivotal role in the activation of inflammatory pathways, increasing the production of inflammatory cytokines, mainly tumor necrosis factor alpha (TNF-α) and IL-6 and inducing miRNA dysregulation." (PMID 36233355, 2022). "TNF-α, as the most common and important inflammatory factor, is a common indicator of metabolic syndrome." (PMID 35360475, 2022). "The mean levels of serum Il-6/TNF-a/MCP-1 were significantly higher in all the types of dyslipidemia among male participants." (PMID 36032093, 2022). "3T3-L1 adipocytes were exposed to lipopolysaccharide (LPS), palmitic acid (PA) and tumor necrosis factor alpha (TNFα) to stimulate inflammation and dyslipidemia." (PMID 36319747, 2022). "It is significant that just recently delphinidin-3-O-glucoside has been recognized as a potential anti-inflammatory of TNF-α signaling, an inflammatory cytokine that is overexpressed in metabolic syndrome." (PMID 35204071, 2022). "In contrast, a clinical study in 25 subjects with metabolic syndrome showed intravenous vit C administration increased the expression of inflammatory-related genes such as TNF-α, Interleukin 4 (IL-4), and Interferon-gamma (IFN-γ) in the mononuclear cells." (PMID 35949307, 2022). "The DRS designed to model diabetic hyperglycemia and dyslipidemia were either ineffective or far less effective in eliciting significant alterations than TNFα or IL-1β." (PMID 35902594, 2022).
metabolic syndrome (continued). "OPG level positively correlates with CRP in adult patients with metabolic syndrome, and TNFα together with IL-1β stimulated production of OPG by human retinal microvascular endothelial cells." (PMID 33604725, 2021). "Quercetin, genistein, and naringenin alleviated TNF-α and IL-6 levels in rats with high-fructose and high-fat diet-induced metabolic syndrome rats, respectively." (PMID 34987591, 2021). "The results showed that intake of L. plantarum significantly reduced the TNF-α level, which is in conformity with a previous study showing the supplementation of L. plantarum lowered the TNF-α concentration in male Wistar rats having metabolic syndrome." (PMID 33828554, 2021). "Similar to other biochemicals in the circulation, ApoA-1 is sensitive to the doxorubicin-induced oxidative damage, leading to dyslipidemia and increased circulating TNF-α in the doxorubicin- injection animals, resulting in cognitive impairment." (PMID 34055643, 2021). "Metabolic dysregulation, including hyperglycemia, dyslipidemia, and adiposity, increases TNF-α levels." (PMID 34199767, 2021). "It has been suggested that abdominal adipose tissue is the major source of plasma PAI-1, as it originates from adipose tissue in response to chronically elevated levels of TNF-α and insulin in individuals with metabolic syndrome." (PMID 34069933, 2021). "Increases in the concentration of either TNF-α or CRP have also been reported alongside dyslipidemia and obesity." (PMID 33731756, 2021). "ApoA-1 is sensitive to the doxorubicin-induced oxidative damage, leading to dyslipidemia and increased circulating TNF-α." (PMID 34055643, 2021). "Recently, in a model of metabolic syndrome, a high-fat diet, supplemented with 12% (w/w) of freeze-dried T. lutea, significantly reduced plasma TNF-α levels and increased IL-10 in abdominal adipose tissue." (PMID 34207952, 2021). "Inflammatory cytokines such as TNF-α, IL-6, and IL-1β play significant roles in the etiology of metabolic syndrome." (PMID 34938803, 2021). "Jun N-terminal kinase and extracellular regulated protein kinases are easily activated by TNF, IL, and ROS, as well as metabolic syndrome, and both play important roles in various processes of physiology and pathology." (PMID 34249992, 2021). "Cross-sectional studies showed that acute phase reactants such as C-reactive protein (CRP) and cytokines (lL-6 and TNF-α) are related to components of the MS, such as BMI, WC, resistance to insulin, hypertension, and dyslipidemia." (PMID 34957175, 2021). "These cytokines, especially TNF-α and leptin, seem to aggravate hypertension, which, together with visceral obesity, dyslipidemia, and hyperglycemia, configure the metabolic syndrome scenario." (PMID 33807959, 2021). "High hsCRP, TNF-α, and TGF-β levels increase the susceptibility to cardiac damage in hypertensive patients with the metabolic syndrome, in whom they are independently related to the LV mass index and diastolic LV dysfunction." (PMID 34671656, 2021). "Current research provides links among dyslipidemia and elevated levels of low-grade chronic inflammatory cytokines, such as interleukin IL-6, TNF-α, and CRP." (PMID 34299655, 2021). "The NF-κB signaling pathway mediated by TNF-α can regulate lipid metabolism, and IL-6 can promote systemic inflammation, leading to metabolic syndrome and abnormal lipid metabolism." (PMID 35047504, 2021). "It includes small sample size and literature regarding serum TNF in the Saudi population’s metabolic syndrome." (PMID 34104151, 2021). "The anti-inflammatory effect of quercetin in metabolic syndrome was previously demonstrated through its effect on TNF-α and adiponectin and the anti-inflammatory effect of the PSO was also demonstrated in previous studies." (PMID 34456723, 2021). "Adiponectin, leptin, resistin, TNF-α and IL-6 are considered as possible serum markers of metabolic syndrome and their expression levels are majorly regulated by SREP-1c and PPAR-γ." (PMID 33917607, 2021).
metabolic syndrome (continued). "Various reports have been documented to explore the relationship between high serum TNF-α expression with different components of impending metabolic syndrome." (PMID 34104151, 2021). "ME alleviated dyslipidemia and lipid accumulation, as well as pro-inflammatory cytokine production such as tumor necrosis factor-α (TNF-α), interleukin 6 (IL-6), and monocyte chemoattractant protein 1 (MCP1) in the WAT." (PMID 34573085, 2021). "A large number of adipocytokines (leptin, adiponectin, visfatin, PAI-1, resistin, TNF-α, and IL-6) are involved in the pathogenesis of metabolic syndrome (MS)." (PMID 33584134, 2021). "In our previous research, we documented the associations of plasma concentrations of interleukin 6 (IL-6) and tumour necrosis factor α (TNF-α), together with its soluble receptors, with components of metabolic syndrome in patients with CAD." (PMID 34679472, 2021). "Expression and/or activity of eNOS substantially decreases in response to classic atherogenic culprits such as chronic inflammation (TNF, interleukin 1, and IFNγ), oxidative stress, hypoxia, hyperglycemia, and dyslipidemias." (PMID 34026871, 2021). "In an ‘ex vivo’ setting, nitrate intake avoids the enhanced expression of CAT and TNFα induced by PMA in PBMCs from metabolic syndrome patients but, on the other hand, it activates the expression of GPx in response to PMA stimulation." (PMID 34198661, 2021). "When comparing within metabolic syndrome subjects, serum levels of IL-10, IL-1α, and TNF-α revealed a trend towards higher levels in subjects with vitamin D deficiency." (PMID 32178228, 2020). "Tumor necrosis factor-α (TNF-α), a pro-inflammatory cytokine that plays a key role in metabolic syndrome and pathological processes." (PMID 32326962, 2020). "In the current study, metabolic syndrome animals showed three-fold rise in TNF-α serum levels while both AM6545 and AM4113 reduced TNF-α to similar levels." (PMID 33138155, 2020). "Here we report that the practice of moderate acute exercise (60–70% of HRmax) for 30 min by metabolic syndrome patients increased TNFα and ICAM1 concentrations but maintained pre-exercise concentrations of IL6 at 30 min post-exercise." (PMID 32646062, 2020). "Adipose tissues produce several proinflammatory cytokines such as TNF-α, leptin, resistin, and adiponectin, which have been suggested as being responsible for linking obesity and metabolic syndrome." (PMID 32823524, 2020). "The adipokines leptin, adiponectin, tumor necrosis factor-alpha (TNF-α), and interleukin 6 (IL-6) might be associated with metabolic syndrome (MetS) in patients with schizophrenia." (PMID 33066473, 2020). "We have reported increased concentrations of the inflammatory cytokine TNF-α in animal models of metabolic syndrome." (PMID 33138155, 2020). "The level of TNF-α is closely related to carotid intima-media layer thickening, dyslipidemia, and AS." (PMID 32365054, 2020). "Metabolic syndrome leads to a higher secretion of inflammatory mediators, such as leptin, tumor necrosis factor alpha (TNF-α), monocyte chemoattractant protein-1 (MCP-1), resistin, and interleukin 6 (IL-6)." (PMID 33123088, 2020). "Since then, many pivotal adipokines, such as adiponectin, resistin, and tumor necrosis factor α (TNF-α), have been extensively studied in metabolism and metabolic syndromes." (PMID 31718027, 2019). "Contrary to the TNFα plasma concentration, the TNFα was reported to be markedly elevated in metabolic syndrome rat induced with fructose and treatment with ferulic acid suppressed the TNFα production." (PMID 31462242, 2019). "TNFα is a central adipokine in metabolic syndrome, and we found an increase in its circulating levels in metabolic syndrome patients, which again positively correlated with the circulating glucose concentrations." (PMID 31109070, 2019).